IL10 (interleukin 10)
Diseases named in the same sentence as IL10 in open-access papers (continued):
Sharing a sentence is not in itself a finding about the gene and the disease.
uremia (11 papers, 2015 to 2025). A clinical syndrome associated with the retention of renal waste products or uremic toxins in the blood. "In uremia, endotoxins and complement activation contribute to increased IL-10 secretion by macrophages and monocytes." (PMID 40108621, 2025). "Data from the literature describe an increase in serum IL-10 levels in ESRD as a way of defending against multiple inflammatory reactions induced in the body by uremia and chronic dialysis." (PMID 41226982, 2025). "As previously noted, high IL‐10/TNFα ratios have been associated with an “anti‐inflammatory state” (e.g., in patients with ARDS or uremia; 26,27)." (PMID 32940965, 2020). "The serum levels of TNF-α, IL-6, and IL-10 in the uremia group presented an increased trend over time, and these cytokine levels were higher than those in the control group at all the investigated time points." (PMID 27493661, 2016). "The high expression of IL-10 in all renal disease groups compared to healthy dogs is consistent with observations in humans in which uremia was reported to influence expression of both pro- and anti-inflammatory cytokines, including IL-10." (PMID 26824356, 2016). "In addition, on both postoperative weeks 8 and 10, the serum level of the anti-inflammatory cytokine IL-10 of the uremia group was also significantly increased when compared with that of the control group (P < 0.05)." (PMID 27493661, 2016). "IL-10 levels are elevated in patients with glomerular diseases, uremia, and hemodialysis." (PMID 26393580, 2015). "The elevation of IL-10 in CKD has been considered an adaptive, counter-regulatory mechanism to control uremia- and dialysis-induced inflammation, that nevertheless results insufficient to completely shut them off." (PMID 28333114, 2017). "In the present study, we also demonstrated that the uremia group presented an increased trend over time in the serum cytokines TNF-α, IL-6, and IL-10, and these cytokines were higher than those in the control group at all the investigated time points." (PMID 27493661, 2016). "Available data suggest that the anti-inflammatory cytokine interleukin-10 (IL-10) and the major pro-inflammatory cytokines IL-6 (IL-6) and TNF-α may play critical roles in uremia." (PMID 36189322, 2022). "Thus, it is unclear that IL-10 should be considered a uremic toxin, as there is little evidence that the levels found in uremia are detrimental." (PMID 28333114, 2017). "The most important is the lack of determination of more serum inflammation (IL-6, IL-10, IL-18, TNF-α), bone metabolic (FGF-23 and bone alkaline phosphatase), and uremia markers." (PMID 36611532, 2022).
viral myocarditis (11 papers, 2014 to 2025). Myocarditis that is caused by an infection with a viral agent. "Andrographolide may improve viral myocarditis by inhibiting the increase in serum TNF-α, hs-CRP and cTnI levels caused by viral myocarditis, activating the IL-10/STAT3 anti-inflammatory pathway, and inhibiting the PI3K/AKT/NF-κB pathway." (PMID 36238575, 2022). "Anti-IL-10 therapy canceled the protective effect mediated by H310A1 infection by inhibiting T regulatory cell response, indicating that IL-10 is the main immunomodulatory factor in viral myocarditis." (PMID 37047468, 2023). "The monocytic myeloid-derived suppressor cells upregulated the percentages of Treg and CD4+ IL-10+ T cells to reduce the inflammatory response in viral myocarditis." (PMID 30176160, 2018). "In this study, we showed increased expression levels of proinflammatory cytokines (TNF-α, IL-6, and MCP-1) as well as antiviral cytokines (IFN-β and IFN-γ) and an anti-inflammatory cytokine (IL-10) due to viral myocarditis in cardiac tissue." (PMID 25374444, 2014). "Moreover, IL‐10–producing B cells were previously found to reduce the proportions of both T helper (Th) 1 and Th17 cells and thereby to ameliorate inflammatory myocardial injury during the early stage of viral myocarditis." (PMID 35005845, 2022). "Our recent studies showed that umifenovir can reduce the expression level of interleukin 10 (IL-10) and the CVB4 viral load in a mouse model of viral myocarditis and alleviate pathological damage in the myocardium." (PMID 36541788, 2023). "Taken together, our data suggest that the early induced IL-10 and IL-10+ CD4+ Tregs in the cecal patch after CVB3 infection intimately regulate intestinal IL-10 and IL-10+ CD4+ Tregs situation, thus exerting an important pro-viral and pro-inflammatory effect in the development of viral myocarditis." (PMID 37896753, 2023).
viral pneumonia (11 papers, 2017 to 2025). Inflammation of the lung parenchyma that is caused by a viral infection. "The result of multivariate logistic analysis indicated that initial plasma IL-10 level, age, and viral pneumonia are independently associated with ICU mortality." (PMID 28432351, 2017). "In human medicine, certain cytokines such as IL-8, TNF-α, and IL-10 have recently been used to differentiate Mycoplasma pneumoniae infection from viral pneumonia in children." (PMID 40703922, 2025). "Further mechanistic studies will be needed to investigate the exact role of BPE-restored IL-10 in treating viral pneumonia inflammation." (PMID 38164360, 2024). "Meanwhile, most of the patients with an AAT/IL-10 ratio of < 65 and less sputum had purely viral pneumonia." (PMID 37876022, 2023). "Additionally, it has been shown that electroacupuncture at BL13 down-regulates the lung index and serum TNF-α levels and up-regulates serum IL-10 levels in mice with viral pneumonia." (PMID 40098935, 2025). "In previous work, we have also discovered increased serum level of IL-10, IL-6, as well as acute-phase proteins (CRP and Serum amyloid A1) in the same patients with SARS-CoV-2 induced viral pneumonia." (PMID 36298646, 2022). "In a study of viral pneumonia, it was found that CD8+Treg cells inhibited the function of CD8+T cells through IL-10." (PMID 35907816, 2022).
age-related macular degeneration (10 papers, 2009 to 2025). Age-related loss of vision in the central portion of the retina (macula), secondary to retinal degeneration. "Firstly, genetic protection against age-related macular degeneration (AMD) was linked to higher IL-1Ra and IL-10 responses to a wide range of pathogens through the CFH locus." (PMID 38714679, 2024). "Our laboratory was interested in exploiting the pro-angiogenic and anti-inflammatory properties of IL-10 in a model of age-related macular degeneration (AMD)." (PMID 19771172, 2009). "Administration of the small molecule, 5,15-di phenyl porphyrin (DPP), a selective inhibitor of IL-10/STAT3 signaling, has been shown to reduce pathologic neovascularization and Age-related Macular Degeneration (AMD) via inhibition of alternative activation and M2 polarization of macrophages." (PMID 34777338, 2021). "In these studies, investigators found that IL-10 activation of STAT3 in macrophages promotes choroidal neovascular angiogenesis, an important pathological event in blindness, resulting from some forms of age-related macular degeneration." (PMID 27491076, 2016).
alcoholic liver diseases (10 papers, 2018 to 2026). A disorder caused by damage to the liver parenchyma due to alcohol consumption. "IL-6 and IL-10 are cytokines with anti-inflammatory and hepatoprotective roles, e.g., in alcoholic liver disease (ALD)." (PMID 40415790, 2025). "Cytokines, namely IL-6, IL-10, and TNF-α, are strongly associated with the development of alcoholic liver diseases according to previous research." (PMID 37759693, 2023). "The effects of IL-10 have been observed in viral or autoimmune hepatitis, alcoholic liver disease, and animal models." (PMID 30123925, 2018). "Indeed, IL-10 may play a protective role in alcoholic liver disease." (PMID 34830373, 2021).
aspergillosis (10 papers, 2015 to 2025). Aspergillosis is an infection, growth, or allergic response caused by the Aspergillus fungus. "In a rat model, aspergillosis was significantly associated with an increase in IL-10 levels, correlating to an increased T helper 2 (Th2) cell response and a decreased Th1 response, resulting in a downregulation of macrophage activity and an increase in host susceptibility to Aspergillus infection." (PMID 35050031, 2022). "Furthermore, the release of IL-10 by Th2 cells has a detrimental effect on protective Th1 responses in aspergillosis models." (PMID 38667922, 2024). "Therefore, polymorphisms of many immune-related genes are associated with susceptibility to aspergillosis, such as tumor necrosis factor receptor 1 (TNFR1), TLR1/4/5/6, Dectin-1, DC-SIGN, IL-8, IL-10, IL-12, IL-4R, IFN-γ, IRF4 and so on." (PMID 35407478, 2022). "The defective IL-10 (anti-inflammatory) response may lead to an exaggerated immune response resulting in allergic form of aspergillosis." (PMID 32047500, 2020). "In mice, the susceptibility to aspergillosis is increased in conditions of TLR3 absence, leading to an increase in the inflammatory process in murine aspergillosis, accompanied by a decrease in the production of IFN-γ, IL-10." (PMID 33194839, 2020). "In addition, IL-10 released by Th2 cells also negatively impacts protective Th1 responses in aspergillosis models, by suppressing pro-inflammatory cytokines and chemokines, inhibiting T-cell activation and IFNγ production, and promoting a Th2 response." (PMID 29371571, 2017). "IL-10 expression was greatly increased after IL-37 treatment in mice with aspergillosis." (PMID 26435567, 2015). "Early in aspergillosis, CD4+CD25+ Treg recruitment is able to control inflammation by neutrophil suppression, mediated by the actions of IL-10 and CTLA-4 on IDO." (PMID 29371571, 2017). "The therapeutic efficacy with micafungin in aspergillosis is strictly induced by the activation of the TLR2/dectin-1 and TLR3/TRIF signaling pathways, which regulate the inflammatory/anti-inflammatory balance during infection, mainly by increasing the production of IL-10 and decreased TNF-α." (PMID 33194839, 2020).
atopic asthma (10 papers, 2010 to 2023). An asthma that is characterized by symptoms that are triggered by an allergic reaction caused by inhaled allergens such as dust mite allergen, pet dander, pollen and mold. "Moreover, a certain IL-10 gene promoter polymorphism was reported to be linked to susceptibility to atopic asthma." (PMID 31336954, 2019). "No further correlations were detected between sCD23 and regulatory or IL‐10‐secreting B cells during pregnancy or the postpartum period of the women with atopic asthma." (PMID 33682259, 2021). "In line with this idea, we observed a positive correlation between BAFF levels and IL‐10 secreting B cells in pregnant women with atopic asthma." (PMID 33682259, 2021). "To gain better insight into Tregs in adult atopic asthma patients we assessed the frequency of Tregs along with those expressing IL-10." (PMID 29507584, 2018). "There is evidence that the number and function of two major subsets of Treg, namely, CD4+CD25+Foxp3+ Tregs and IL-10 producing Tregs, are impaired or altered in patients with atopic asthma compared with healthy individuals." (PMID 21197090, 2010). "Atopic asthma patients generally have lower levels of IL-10 compared with healthy individuals." (PMID 37760982, 2023). "In fact, increased BAFF levels during pregnancy may contribute to the maintenance of a regulated environment by promoting IL‐10 secretion in B cells, as sustained by observations of both healthy pregnant women and those with atopic asthma." (PMID 33682259, 2021). "In this study intracellular cytokine expression of IL-2, IL-4, IL-10, IL-13, IFN-γ, and TNF-α in CD4+ and CD8+ T cells in children with atopic asthma were measured by flow cytometry." (PMID 21197090, 2010).
Dengue hemorrhagic fever (10 papers, 2013 to 2024). A serious condition caused by Dengue virus infection. "Likewise, high levels of IL-10 during early illness were an indicator of an altered antiviral response, and this association was particularly observed in patients who progressed to dengue hemorrhagic fever." (PMID 39457019, 2024). "High serum values of IL-10 were found in patients with a severe course of dengue hemorrhagic fever and Argentine hemorrhagic fever." (PMID 35337004, 2022). "Elevated levels of IL-10 were reported in Dengue hemorrhagic fever and in fatal cases of EVD too." (PMID 31357521, 2019). "Patients who experienced severe COVID-19 pneumonia and dengue hemorrhagic fever (DHF) had notably higher levels of IL-6, IL-10, and MIP3α during disease onset compared to those with mild disease." (PMID 39519178, 2024).
gastric tumor (10 papers, 2015 to 2025). "IL-10 was found to be significantly elevated in both gastric tumor tissues and the serum of afflicted individuals, with TAMs identified as the primary source." (PMID 39664377, 2024). "We detected an increase in Bregs producing IL-10 both in peripheral blood mononuclear cells (PBMCs) and in gastric tumors." (PMID 26378021, 2015). "The experiment demonstrated that moxibustion combined with chemotherapy significantly decreased serum IL-10 and TGF-β1 levels in gastric tumor-bearing mice compared to the model group." (PMID 41438510, 2025). "In this study, we investigated the gastric tumor response to radiation therapy, based on the Sting signal, IFNB1, TNFα, CXCL-9 as well as IL-10 gene expression, infiltration of DCs, Th and Teff cells in the tumor microenvironment, and PD-1/PD-L1 expression after radiation therapy." (PMID 32960261, 2020). "As for the significantly higher IL-10 production detected in tumor tissues than that in non-tumor tissues and a positive correlation between CD45RA−CCR7− Treg infiltration and IL-10 production within gastric tumors observed." (PMID 28817117, 2017).
Graves disease (10 papers, 2012 to 2025). Graves' disease is an autoimmune disorder that leads to overactivity of the thyroid gland (hyperthyroidism).It is caused by an abnormal immune system response that causes the thyroid gland to produce too much thyroid hormones. "In Graves’ disease, Th2 lymphocytes are infiltrated and IL-4 and IL-10 are produced, causing the expression of anti-apoptotic molecules and also, their resistance to apoptosis through CD95." (PMID 33193078, 2020). "In addition, an association between IL-10 polymorphism and Graves’ disease has been reported in the Turkish population." (PMID 25667655, 2015). "In conclusion, the expression levels and genetic polymorphisms of IL-2 and IL-10 may be potential biomarkers for the incidence of Graves’ disease in the population studied." (PMID 25667655, 2015). "Another study reported elevated levels of a rare subset of CD38-FoxP3+IL-10+ Bregs and decreased levels of CD38+FoxP3+IL-10+ Bregs in pediatric patients with Graves’ disease." (PMID 40458534, 2025). "Moreover, reduced values for CD38+ cells with co-expression of Foxp3 and IL-10 were reported in Graves’ disease pediatric patients." (PMID 34681587, 2021). "Here, we found that a more significant role could be attributed to regulatory B cells characterized by Foxp3 and IL-10 expression, as these subpopulations seemed to play the most crucial role in the course of Graves’ disease therapy." (PMID 34681587, 2021). "The aim of the present study was to determine whether the expression levels of interleukin (IL)-2 and IL-10 may be used as biological markers in Graves’ disease (GD) patients." (PMID 25667655, 2015). "Presumably, expansion of CD38- B cells with Foxp3+ and/or IL-10 expression counteracts reduced numbers of CD38+Foxp3+IL-10+ Bregs and is a sign of a compensatory mechanism aimed at the reduction in autoimmune reactions related to Graves’ disease." (PMID 34681587, 2021). "A study of both types of patients (Graves’ disease and HT) showed a tendency for decreased numbers of CD19+CD24+CD27+IL-10+ and CD19+IL-10+ B cells, which could be responsible for immune imbalance and AITDs." (PMID 33936028, 2021).
keratitis (10 papers, 2008 to 2024). A corneal disease that is characterized by inflammation of the cornea. "The current study confirmed the lack of association of the SNP rs1800872, rs1800896 and rs6703630 in IL10 with risk of keratitis or severe keratitis, and found two novel haplotypes of IL10 were associated with risk of MK compared with controls." (PMID 36422638, 2022). "The first study to examine whether SNPs in interleukins were associated with keratitis examined several SNPs in IL10." (PMID 36422638, 2022). "The IL10 promotor SNP rs6693899 allele C, which had been associated with the production of high levels of IL-10, was associated with better clinical outcome of keratitis, whereas allele A of rs6693899 was associated with poor clinical outcomes." (PMID 36422638, 2022). "The impact of PL on the expression of HMGB1, LOX-1, TNF-α, IL-1β, IL-6, IL-10 and ROS in A. fumigatus keratitis was investigated using RT-PCR, ELISA, Western blot, and Reactive oxygen species (ROS) assay." (PMID 38655086, 2024). "Buccal swab samples were collected from 88 keratitis patients, amongst them 25 were severe and 185 were healthy contact lens users, to carry out DNA extraction and SNP genotyping by pyrosequencing for IL-10 and IL-17." (PMID 35328532, 2022). "A retrospective study was performed to evaluate contact lens keratitis by assessing the role of SNPs in IL-10 and IL-17 genes." (PMID 35328532, 2022). "As per mirror of the biomolecular changes occurring after leucocytes infiltration, specific ELISA kits revealed a marked increase of both the PMN‐produced cytokine CXCL1/KC and the macrophage‐produced IL‐10 24 hours after the induction of keratitis." (PMID 33058526, 2020). "In an aspergillus fumigatus keratitis mouse model, MaR1 was found to increase the expression of anti-inflammatory cytokine IL-10." (PMID 31680874, 2019). "In studies of animal models on the herpes simplex virus-infected keratitis, cytokines such as IL-1β, IL-6, IL-8, IL-10, IL-12, and IFN-γ were demonstrated to play a predominant role in disease development." (PMID 29673332, 2018). "The current study was able to replicate the lack of association of the IL-10 SNPs rs1800872, rs1800896, and rs6703630 with risk of keratitis or severe keratitis." (PMID 36422638, 2022). "Therefore, a mouse model of lipopolysaccharide (LPS)‐induced keratitis has been to investigate the RvD1 actions, by monitoring the local inflammatory components such as KC, IL‐10 and macrophage phenotypes." (PMID 33058526, 2020). "Although we did not see elevation of mBD3, nor test mBD1 after GLY treatment, we did observe reduction in IL-10 (mRNA), suggesting that a similar mechanism may be operative in the keratitis model." (PMID 27792814, 2016). "However, approximately one-third of genes involved in IL-10 signaling were significantly upregulated during Candida albicans keratitis." (PMID 18843377, 2008). "Whilst no single SNP in the IL10 gene was different between cases and controls, two haplotypes of IL10 occurred more frequently in cases of microbial keratitis than controls, and one of these also occurred more frequently in cases of microbial keratitis compared with sterile keratitis." (PMID 36422638, 2022).